LGI1 (leucine rich glioma inactivated 1)
Diseases named in the same sentence as LGI1 in open-access papers (continued):
Sharing a sentence is not in itself a finding about the gene and the disease.
encephalitis (continued). "Given that FBDS occur early and have a high incidence in LGI1 antibody encephalitis, we suggest that all patients with FBDS be examined for increased LGI1 antibody titers as soon as possible, and upon definitive diagnosis, immunotherapy be initiated immediately." (PMID 29980179, 2018). "Stainings for immunoglobulin deposits and complement activation were negative, indicating that no antibody-mediated response occurred, as can be seen in encephalitis with antibodies against surface antigens like anti-LGI1 or anti-CASPR2." (PMID 28554330, 2017). "In LGI1 antibody-mediated encephalitis but not in NMDAR antibody encephalitis, for example, there is consistent evidence of complement deposition and associated cell death in patient brain tissue." (PMID 26667479, 2016). "The importance of being aware of and recognizing FDBS, does not hinge only ondistinguishing patients with anti-LGI1 encephalitis and CJD." (PMID 29213481, 2016). "To date, there have been no reported cases of SLE with anti-LGI-1 encephalitis." (PMID 39965877, 2025). "In patients with anti-NMDAR Ab-mediated encephalitis, age typically has not predicted functional outcomes, and results are mixed in patients with anti-LGI1 encephalitis, though a study of antibody-negative cases found age more than 60 to be a marker of poor prognosis." (PMID 40281286, 2025). "This patient had a negative CSF analysis and presented with paroxysmal dystonic episodes related to a large thrombosed basilar aneurysm with mass effect on the brainstem, without any other neurological sign consistent with anti-LGI1 or anti GABABR aAbs encephalitis after extensive investigations." (PMID 40303411, 2025). "However, compared with the autoimmune encephalitis group, especially the LGI1-antibody encephalitis group and GABAB-antibody encephalitis group, limited differences were observed in the results of blood and CSF examinations in the COVID-19-related encephalitis group." (PMID 38772979, 2024). "HS may contribute to a poorer outcome of anti-LGI1 encephalitis, even though this could not be demonstrated in our limited number of patients." (PMID 39105896, 2024). "Apart from anti-CASPR2 encephalitis, other subtypes such as anti-NMDAR, anti-LGI1, anti-GAD65, and anti-GABABR encephalitis exhibited NLR values that were largely consistent with SE incidence, suggesting that the predictive value of NLR may vary across different AE subtypes." (PMID 39539648, 2024). "Although FBDS are pathognomic of anti-LGI1 encephalitis, the sudden onset of involuntary movements should prompt clinicians to recommend a wide panel of investigations, including investigating for anti-LGI1 antibodies, even in the absence of MRI-detectable brain lesions." (PMID 37033571, 2023). "No patient with anti-LGI1 or anti-CASPR2 encephalitis had tumour." (PMID 38152405, 2023). "Nevertheless, we believe that it is not the anti-LGI1 encephalitis that is not well controlled, but the static structural brain damage left after treatment, the atrophy in the left frontotemporal lobe, that result in structural drug-resistant epilepsy and intellectual disability." (PMID 37179544, 2023). "Thus, given the strong ability of CNN models to mine crucial features and subtle information, these models may accurately characterize the properties of PET images of both LGI1 and GABAB receptor antibody encephalitis." (PMID 37592180, 2023). "However, it remains unclear whether LGI1 and GABAB receptor antibody encephalitis can be accurately discriminated using DL models based on PET images." (PMID 37592180, 2023). "Importantly, miR-2467-5p expression in ABs and microvesicles did not vary between LGI1 encephalitis cases and HDs." (PMID 37644514, 2023).
encephalitis (continued). "FBDS, a pathognomonic manifestation of anti-LGI1 encephalitis, can be EEG negative, even though some patients show an abnormal EEG pattern consisting of a large slow wave in the frontopolar, frontal or central area preceding the tonic contraction of the contralateral arm by at least 700 ms." (PMID 36672553, 2022). "The testing cohort included another 16 healthy participants and 16 patients with anti-LGI1 encephalitis whose metabolic abnormality was not able to be visibly detected in the medial temporal lobe and the basal ganglia in their PET images [non-completely detectable (non-CD) patients]." (PMID 35711267, 2022). "First, anti-NMDAR encephalitis is just one of the autoimmune encephalitis types, which also includes α-amino-3-hydroxy-5-methyl-4-isoxazolepropionic acid receptor (AMPAR), γ-aminobutyric acid (GABA), and leucine-rich, glioma-inactivated 1 (LGI1) et.al, among others." (PMID 35717162, 2022). "No tumors were detected in both the anti-LGI1 encephalitis and anti-CASPR2 encephalitis groups." (PMID 36211351, 2022). "Pathways associated with SOCS1, SHIP1, C/EBP-β, and IL13Rα1 signaling cascades might regulate the development CASPR2 encephalitis but not LGI1 encephalitis." (PMID 35083659, 2022). "This may indicate that patients with anti-LGI1/CASPR2-encephalitis do not further improve at later time points." (PMID 34093529, 2021). "In all 55 patients with anti-LGI1 encephalitis, no tumors were observed." (PMID 34135845, 2021). "For example, patients with LGI1 antibodies may have a normal MRI and CSF, the reason why Graus and colleagues coined the term LGI1 encephalopathy (rather than encephalitis)." (PMID 33816660, 2021). "Currently, factors related to the prognosis of anti-LGI1 encephalitis are still lacking." (PMID 34168612, 2021). "Unlike anti-LGI1 encephalitis, which is usually restricted to MTL, viral encephalitis may develop more extensive MRI abnormalities in frontal, occipital, or parietal lobes." (PMID 33510707, 2020). "Interestingly, functional connectivity analyses also show characteristic alterations in several large-scale networks, suggesting that LGI1 encephalitis is not confined to the limbic system." (PMID 32873782, 2020). "Interestingly, previous studies showed that anti-LGI1 encephalitis was highly associated with several human leukocyte antigen (HLA) class II alleles, whereas anti-NMDAR encephalitis was not." (PMID 31736858, 2019). "However, the encephalitis group could be divided between those with otherwise seronegative LE and high GAD-Ab values (all but one > 10,000 IU/mL), and those with other encephalitis syndromes (e.g. LGI1-Ab or Rasmussen’s) whose GAD-Ab were all < 2000 IU/mL." (PMID 39985693, 2025). "Therefore, mRS may not adequately reflect morbidity in patients with anti-LGI1 Ab-mediated encephalitis." (PMID 40281286, 2025). "This may explain two clinical findings as being detached from the ab effect: (i) the low ab titers, in general, found in LGI-1 AE that were contradictory with the CNS damage occurring, and (ii) that although sometimes no LGI1 abs were found in the CSF, encephalitis occurred." (PMID 38473828, 2024). "A recent study found the abnormal intensity of the PET signal in some areas within the medial temporal lobe and/or the basal ganglia for patients with autoimmune encephalitis (including many patients with anti-LGI1 encephalitis) who could not be identified by visual inspection." (PMID 35711267, 2022). "Furthermore, as the research deepens, we have increasingly realized that the long-term prognosis of anti-LGI1 encephalitis may not be that good." (PMID 34168612, 2021). "Importantly, we could show that BBB disturbance in LGI1 encephalitis does not depend on T cell infiltrates, which were present brain-wide." (PMID 29093718, 2017).
encephalitis (continued). "Results in our study demonstrated that miRNAs 128-5p was found to be over-expressed in CASPR2 and LGI1 AE cases, and miR-155-5p was found highly expressed in CASPR2 encephalitis, while not in LGI1 encephalitis." (PMID 35083659, 2022). "Data on the analysis of mortality in patients with anti-NMDAR, anti-LGI1, and anti-GABABR encephalitis are lacking in Northeast China." (PMID 35320933, 2022). "None of the eight patients tested for SARS-CoV-2 PCR in CSF were positive, and none of the autoantibodies seen in autoimmune forms of encephalitis (NMDAR, LGI1) or encephalomyelitis (AQP4, MOG) were detected in serum or CSF samples." (PMID 32637987, 2020). "A total of 103 children with AE, including 89 with anti-NMDAR encephalitis, two with anti-LGI1 encephalitis, one with anti-CASPR2 encephalitis, and 11 with autoantibody-negative but probable AE, were followed up." (PMID 31507515, 2019). "Also, in patients with anti-LGI1/CASPR2 antibody-mediated encephalitis, ivMP + IVIG or ivMP + PE treatment did not result in a significantly different mRS outcome (anti-NMDAR p = 0.80; anti-LGI1/CASPR2 p = 0.38)." (PMID 40131535, 2025). "Which mechanism at the molecular level is involved in anti-NMDAR encephalitis remains unclear, as does whether or not BBB dysfunction occurs in other types of AE with anti-LGI-1, anti-CASPR2, or anti-GABAbR autoantibodies." (PMID 39408955, 2024). "However, the high anti-VGKCC Ab titers with an average of 828 pmol/l are comparable with the concentrations usually observed in anti-LGI1 encephalitis case series and higher than in patients with anti-VGKCC Abs without LGI1 or CASPR2 abs." (PMID 32892761, 2022).
autoimmune encephalitis (157 papers, 2014 to 2026). Inflammation of the brain secondary to an immune response triggered by the body itself. "Background and Aims: Autoimmune encephalitis associated with LGI1 antibodies is a rare and potentially severe condition, often linked to paraneoplastic syndromes." (PMID 40542608, 2025). "This case underscores SNHL as a potentially significant yet rare manifestation of LGI-1 antibody-associated autoimmune encephalitis." (PMID 40904981, 2025). "For example, antibodies against neuronal surface or synaptic proteins, such as anti-NMDA receptor and anti-LGI1 antibodies, have been associated with behavioral changes, cognitive dysfunction, and delirium-like manifestations in autoimmune encephalitis." (PMID 40740958, 2025). "Individual case reports have confirmed efficacy in anti-LGI1-associated autoimmune encephalitis, further supporting the broad applicability of FcRn antagonism across different antibody-mediated neurological syndromes." (PMID 41462987, 2025). "Leucine‐rich glioma‐inactivated‐1 (LGI1) antibodies are among the most frequently detected cell‐surface anti‐neuronal antibodies causing autoimmune encephalitis (AE)." (PMID 40781580, 2025). "One of these is anti-LGI1 limbic encephalitis (anti-LGI1 LE), a unique type of autoimmune encephalitis that mainly affects the medial temporal lobe and causes seizures and memory loss." (PMID 40271344, 2025). "Anti-neural antibodies have been identified as key diagnostic biomarkers for autoimmune diseases of the central nervous system, such as the pathogenic roles of anti-NMDAR and anti-LGI1 antibodies in autoimmune encephalitis, and anti-AQP4 antibodies in NMOSD." (PMID 39965877, 2025). "Anti-LGI1 antibodies, as one of the confirmed pathogenic antibodies for autoimmune encephalitis, are produced by peripheral B cells." (PMID 39965877, 2025). "This case emphasizes the clinical spectrum of LGI-1 antibody-associated autoimmune encephalitis by highlighting SNHL as a significant yet uncommon complication." (PMID 40904981, 2025). "Leucine-rich glioma-inactivated 1 (LGI-1) antibody-associated autoimmune encephalitis is a rare neurologic disorder primarily presenting with memory impairment, behavioral changes, and seizures." (PMID 40904981, 2025). "Efgartigimod has already been used to treat other autoimmune disorders apart from myasthenia gravis, such as neuromyelitis optic spectrum disorder and anti-LGI1-associated autoimmune encephalitis." (PMID 40356636, 2025). "Autoantibodies against the protein leucine-rich glioma inactivated 1 (LGI1) cause the most common subtype of autoimmune encephalitis with predominant involvement of the limbic system, associated with seizures and memory deficits." (PMID 39141878, 2024). "There are only few case reports describing an association between squamous cell lung cancer and LGI1 autoimmune encephalitis." (PMID 39734683, 2024). "Kenta Orimo and others have reported a case of Anti-leucine-rich glioma inactivated 1-associated autoimmune encephalitis in which the patient developed severe orthostatic hypotension 5 years after clinical recovery." (PMID 37861560, 2023). "Anti-leucine-rich glioma-inactivated 1 limbic encephalitis (Anti-LGI 1 LE) is a subtype of autoimmune encephalitis (AE) and the most common cause of limbic encephalitis (LE)." (PMID 37069884, 2023). "Since the pioneering work by Dalmau's group in 2010, anti-LGI1 autoimmune encephalitis (AE) has been recognized as the most common cause of limbic encephalitis and the second most common cause of AE." (PMID 40217477, 2023). "Anti-leucine glioma-inactivated protein 1 (anti-LGI1) autoimmune encephalitis (AE) presents as subacute memory loss, behavioral changes, and seizures." (PMID 37264220, 2023). "Autoimmune encephalitis (AIE) associated with antibodies directed against the leucine-rich glioma inactivated 1 (LGI1) protein is the second most common AIE and is responsible for deleterious neocortical and limbic epileptic seizures." (PMID 36849262, 2023).
autoimmune encephalitis (continued). "Autoimmune encephalitis (AE) associated with autoantibodies against leucine-rich glioma-inactivated protein-1 (LGI1) can present with faciobrachial dystonic seizures (FBDS) and/or limbic encephalitis (LE)." (PMID 36672216, 2023). "Detection of Leucine-rich glioma inactivated 1 (LGI1) antibodies in patients with suspected autoimmune encephalitis is important for diagnostic confirmation and prompt implementation of immunomodulatory treatment." (PMID 36591253, 2022). "Leucine-rich glioma inactivated 1 (LGI1) IgG is one of the most common pathogenic neural specific autoantibodies associated with autoimmune encephalitis in adults." (PMID 36304459, 2022). "Autoimmune encephalitis (AE) associated with leucine-rich glioma-inactivated 1 (LGI1) antibody, described a decade ago, is a potentially treatable and recidivistic subtype of AE." (PMID 32581996, 2020). "Absence of oligoclonal banding or hypercellularity should not preclude the disease, as this absence is frequently reported in other types of autoimmune encephalitis (e.g., contactin-associated proteinlike 2 or leucine-rich glioma inactivated 1 autoantibodies)." (PMID 32709734, 2020). "All of the four patient were seronegative and CSF-negative for anti-GABABR, anti-AMPA1, anti-AMPA2, anti-CASPR2, and anti-LGI1 antibodies, which are antibodies known to cause autoimmune encephalitis." (PMID 31866928, 2019). "Some reports found that anti-LGI1 was presumed to be the second most common cause of autoimmune encephalitis among the neuronal surface antibodies group." (PMID 31694559, 2019). "Anti-CASPR2- and -LGI1-associated autoimmune encephalitis and tick-borne virus encephalitis presented particular diagnostic pitfalls." (PMID 29951031, 2018). "Pathogenic autoantibodies targeting the recently identified leucine rich glioma inactivated 1 protein and the subunit 1 of the N-methyl-D-aspartate receptor induce autoimmune encephalitis." (PMID 24950993, 2014). "Leucine-rich glioma-inactivated 1 (LGI-1) antibody-associated autoimmune encephalitis is a rare neurologic disorder characterized by subacute onset of neuropsychiatric symptoms, including memory impairment, behavioral changes, and seizures, most notably faciobrachial dystonic seizures." (PMID 40904981, 2025). "However, autoimmune encephalitis, which is characterized by ictal piloerection, an autonomic seizure manifestation, is frequently associated with anti-LGI1 antibodies." (PMID 40958893, 2025). "In recent years, significant progress has been made in the study of anti-neuronal antibodies, such as anti-N-methyl-D-aspartate receptor (anti-NMDAR) and anti-leucine-rich glioma-inactivated 1 (anti-LGI1) antibodies, which have been confirmed as pathogenic antibodies for autoimmune encephalitis." (PMID 39965877, 2025). "Relapses occur in 15%–25% of patients with leucine-rich glioma-inactivated 1 antibody (LGI1-Ab) autoimmune encephalitis and may cause additional disability." (PMID 38603771, 2024). "Clinicians should be aware that persistent hiccups might be one of the initial manifestations of LGI1 subtype of voltage-gated potassium channel complex antibody associated autoimmune encephalitis." (PMID 35896991, 2022). "Autoimmune encephalitis (AE) associated with anti‐LGI1 antibodies often involves the limbic system and is characterized by symptoms of medial temporal lobe (MTL) damage (drug‐resistant epilepsy, cognitive impairment, behavioral abnormalities, etc.), sleep dysfunctions and autonomic dysfunctions." (PMID 34291554, 2021). "PURPOSE: To explore whether detecting local astrogliosis using [18F]fluorodeprenyl-D2 ([18F]F-DED) positron-emission-tomography (PET) uncovers and monitors inflammatory lesions in patients with anti-leucine-rich glioma-inactivated 1 antibody (LGI1-ab) associated autoimmune encephalitis (AE)." (PMID 41003762, 2025). "Autoimmune encephalitis-like presentations were identified with CNS antibodies against LGI1, GAD65, CV2 and Ma2." (PMID 41436581, 2026).